BRCA1 (BRCA1 DNA repair associated)
Diseases named in the same sentence as BRCA1 in open-access papers (continued):
Sharing a sentence is not in itself a finding about the gene and the disease.
tumor (continued). "The failure to detect a BRCA1 deletion in one of the tumours that exhibited absent or markedly reduced BRCA1 expression could mean that promoter hypermethylation is present on both alleles, thereby alleviating any selection pressure for deletion at the BRCA1 locus." (PMID 16846527, 2006). "The majority of the BRCA1 methylated tumours were found to have absent or markedly reduced BRCA1 expression, suggesting transcriptional silencing by epigenetic modifications." (PMID 16846527, 2006). "None of the four tumours exhibited BRCA1 deletion by FISH and only one displayed AI at the BRCA1 locus." (PMID 16846527, 2006). "Almost all BRCA1 methylated tumours with absent/markedly reduced BRCA1 expression (8/9) displayed BRCA1 deletion." (PMID 16846527, 2006). "In a recent study, nodal status was found to be correlated with tumour size in BRCA-1 negative but not in BRCA-1 positive patients." (PMID 15996267, 2005). "However, among both BRCA1 and BRCA2 families, tumours from older patients form subgroups that are distinctly different from those of the younger patients." (PMID 15987451, 2005). "In this study, the independent markers that distinguished BRCA1 carrier tumours from familial non-BRCA1/2 tumours were earlier age of diagnosis, negative PgR status and higher grade." (PMID 15642173, 2005). "BRCA1-related tumours can have distinct morphological features, similar, if not identical, to ‘medullary’ carcinoma." (PMID 15700031, 2005). "BRCA2 cases did not have such distinctive features compared with non-BRCA1/2 tumours or with unselected control tumours." (PMID 15642173, 2005). "Importantly, these inhibitory effects were dependent on BRCA1 as BRCA1 knockout cells did not demonstrate anti-tumor characteristics." (PMID 41327312, 2025). "We showed that loss of function events in BRCA1/2 comprising missense‐ and frameshift mutations, CN‐losses, as well as inactivating BRCA2 gene fusions can be associated with an elevated GIS independent of the respective tumor entity." (PMID 40278800, 2025). "In the OV_062 patient‐derived xenograft model without BRCA1 mutations but with MRE11A mutations and a high HRD score, venadaparib demonstrated a statistically significant tumor growth inhibitory effect in comparison with the control group and was superior to olaparib (100 mg/kg)." (PMID 39945311, 2025). "Next-generation sequencing analysis of the locally recurrent tumor as well as the pleural metastasis revealed a BRCA2 mutation in exon 11 (p.N1279S), which was somatic, given that germline testing for BRCA1 and BRCA2 revealed no mutations in either of these genes." (PMID 39392573, 2025). "Mouse 4T1 cells with and without siRNA-mediated BRCA1–/– were inoculated in the fat pad of mice, Olaparib was administrated alone or in combination with GSK3Bi lithium, and the tumor volumes and weights were measured at day 14 after Olaparib." (PMID 41243969, 2025). "Our findings suggest that the absence of BRCA1 or BRCA2, and thus deficient repair, leads to gene mutation and tumor initiation through the emergence of transcriptionally associated DSBs in genes categorized as tumor suppressors and proto-oncogenes." (PMID 41350536, 2025). "Moreover, the involvement of BRCA1 and BRCA2 in other cellular functions—such as chromatin remodeling and regulation of gene transcription—may further influence tumor development." (PMID 41373813, 2025). "This non-canonical tumor-suppressive function expands the role of BRCA1 beyond DNA damage repair." (PMID 40342999, 2025).
tumor (continued). "However, a comprehensive view of the tumor microenvironment (TME) and the interplay of tumor, immune, and stromal cells of BRCA1 mutated tumors have not yet been described." (PMID 40904511, 2025). "Furthermore, our results indicated that high levels of BRCA1 are related to a decrease in level of killer immune cells, such as natural killer (NK) cells, macrophages, CD8+ T cells, and plasma-like dendritic cells (pDCs) within the tumor microenvironment." (PMID 38224491, 2024). "Moreover, HRD and HRI cell lines had a significantly higher %rc of SBS3 than BRCA1/2-mutant HRP cell lines which could have been accumulated ex vivo, after the tumor was removed from the patient." (PMID 38398132, 2024). "Combined with the result of the similar distribution of sTILs across the BRCA1 status, this stronger association suggests that sTIL compositions or spatial relationships with the tumor cells might differ between patients with and without tumor BRCA1-PM." (PMID 38191387, 2024). "PARP inhibition is synthetic lethal with deleterious BRCA1 and BRCA2 mutations because homologous recombination repair (HRR) cannot restore these double-strand breaks, introducing genome instability by nonhomologous end joining or leading to tumor cell death." (PMID 39669575, 2024). "Finally, recent findings by us assessing tumor and WBC BRCA1 methylation in concert suggested about 20% of all TNBC and ER low-expression tumors may arise from cells harboring constitutional BRCA1 hypermethylation." (PMID 40225940, 2024). "We could observe that BRCA1 and BLM were also expressed higher in high-CDK2 tumours." (PMID 38732271, 2024). "If BRCA1/2 testing has not identified a reportable variant, then HRD testing may be recommended if available, to identify tumours eligible for PARPi." (PMID 38443545, 2024). "This is supported by findings of Silver and co-workers, who observed a better response to cisplatin in patients with TNBC when the BRCA1 promoter was hypermethylated, and hence, mRNA levels were lower in the tumor tissue compared with tumors without BRCA1 promoter methylation." (PMID 38256203, 2024). "Published data suggest BRCA1/2 germline mutations do not consistently predict favorable responses to PARP inhibitors, suggesting that other factors beyond tumor mutation status may be at play." (PMID 38929955, 2024). "The tumour (tumour 11) with a somatic BRCA1 missense VUS and RAD51D c.202G > A variant were not classified as BRCA1-Like supporting that this tumour is driven by RAD51D and not BRCA1." (PMID 37316882, 2023). "Notably, HuR levels were even higher in BRCA1 (63%) and BRCA2 (62%) tumours and associated with a non-significant reduction in survival in BRCA2 mutation carriers." (PMID 36831687, 2023). "Furthermore, in the BRCA1 subset, CXCL10-positive expression showed a worse prognosis, suggesting that the axis may serve as a potential target in these tumours." (PMID 36831687, 2023). "Moreover, it has been shown that in a certain group of patients with BRCA1/BRCA2 wild type, they present an immune profile of the tumor showing the expression of PD-1/PDL-1 that would benefit from the treatment of iPARP associated with immunotherapy directed at these two biomarkers." (PMID 37444580, 2023). "On the contrary, the possibility exists that for some patients harboring BRCA1 methylation in the tumor tissue but not in WBC, methylation in the WBCs below the sensitivity of our assay may be present." (PMID 38053165, 2023). "For example, PI3K inhibitors can down-regulate BRCA1/2 and induce HRD, and mTOR inhibitors induce inhibition of DNA double strand break (DSB) repair protein SUV39H1, thus inhibiting the expression of HRR gene so as to improve the anti-tumor effect of PARP inhibitors." (PMID 36611214, 2023).
tumor (continued). "In 3 PDX models from the responder group without BRCA1/2 mutations or BRCA1 promoter methylation, we identified mutations in the DDR genes XRCC3 (HBCx-14), TONSL (HBCx-33) and ORC1 (T302), that were present also in the matched patients’ primary tumours." (PMID 37029129, 2023). "Several study limitations were noted, however, and although there was high concordance between germline and tumour BRCA1/2mut, with 82.6% LOH of BRCA1/2, there was unknown methylation status of BRCA1/2 wild-type (wt) and HRR genes, and a lack of power due to small patient numbers in some subgroups." (PMID 36831687, 2023). "In addition, transcriptional crosstalk between BRCA1 and GR exists, although its impact on tumor phenotypes and clinical outcomes has not yet been completely clarified." (PMID 37189400, 2023). "Thus, while the number of OCMs fully analysed to date is still relatively small, there is no obvious evidence yet of a selection bias against BRCA1/2-mutant or HRD tumours." (PMID 37592171, 2023). "The study identified 4 (13%) non-BRCA1/BRCA2 tumours with high BRCA1/BRCA2 HRDetect scores that could not be explained by promotor methylation or somatic mutations." (PMID 37316882, 2023). "In the non-HRD group, there were no BRCA1/2 altered tumours." (PMID 37029129, 2023). "In addition, defective BRCA1/BRCA2 in tumor cells may also lead to failure of DSB repair by the HRR pathway, resulting in massive tumor cell death." (PMID 37305685, 2023). "The absence of germline pathogenic variants in non-BRCA1/2 HRR genes in women aged ≥80, combined with the fact that only 50% of these variants were found in women with a GIS-positive tumour, suggest germline multi-gene panel testing has limited value in women aged ≥80 regardless of GIS status." (PMID 36765687, 2023). "Adjuvant chemotherapy indeed enhanced disease-free survival and overall survival in stage III patients, who had only BRCA1-negative tumours (p < 0.001, p < 0.001, respectively), but not in patients with BRCA1-positive tumours (p = 0.236, p = 0.148, respectively)." (PMID 37568604, 2023). "Among individuals harboring WBC but not tumor BRCA1 methylation (n = 27), 17 revealed small traces of BRCA1-methylated cells in the tumor biopsies, below the defined threshold for classification of tumors as methylation-positive but above the methylation threshold applied to WBC samples." (PMID 38053165, 2023). "50% of tumours in patients having VUS in BRCA1/2 genes were hormone receptor negative." (PMID 37277882, 2023). "We have studied the circular RNA/messenger RNA pair in BRCA1- and BRCA2-related breast tumorigenesis using an innovative dedicated technique and have shown for the first time that there is an imbalance in the circular RNA/messenger RNA ratio between healthy and tumor breast tissues." (PMID 37046838, 2023). "Furthermore, we hypothesize that ATR inhibition results in anti-tumor activity in DDR alterations beyond ATM, such as BRCA1/2 and others." (PMID 37277454, 2023). "Thus, 15.2% (95% CI 7.5–26.1%) of all TNBCs revealed concordant tumor and WBC BRCA1 methylation." (PMID 38053165, 2023). "BRCA1 expression was not correlated with any clinicopathological parameters in CNC patients (p > 0.05), and the expression in BLBC was only associated with tumor size (p < 0.05)." (PMID 37114130, 2023).
tumor (continued). "PARP and WEE1 inhibitors in combination is not sufficient to eradicate BRCA1/2 wild-type TNBC tumours regardless of whether they have low (AT3, 4T1ch9) or moderate (AT3OVA) levels of pre-exsiting TILs." (PMID 37582853, 2023). "In addition, BRCA1 haploinsufficiency upregulates RANKL expression and cell proliferation, which contributes significantly to TNBC tumorigenesis from the cell-of-origin, and RANKL inhibition markedly attenuates tumor onset." (PMID 35327946, 2022). "However, these properties associated with Niraparib do not explain why it also effectively kills tumor cells with wild-type BRCA1/2." (PMID 36324587, 2022). "Therefore, iNOS-induced NO indirectly suppresses BRCA1 and BRCA2 tumor suppressor functions." (PMID 35740092, 2022). "No BRCA1 alterations were found in 22% of the tumor samples sequenced with the GeneReader, in 10% with the Ion S5TM and in 4% with the MiSeqTM, whereas no BRCA2 alterations were detected in 2% of the tumor samples sequenced with the GeneReader, but not with the Ion S5TM or the MiSeqTM." (PMID 35251494, 2022). "Those authors not only demonstrated that cyclic niraparib in vitro treatment of BRCA1-/- cells gives rise to multiple genetically and functionally heterogeneous PARPi-resistant clones, but that similar clonal heterogeneity was observed in a HGSOC patient’s tumor biopsy resistant to PARPi." (PMID 35406579, 2022). "They investigated the expression patterns of molecules such as the immuno-related protein BRCA-1 and the anti-inflammatory and antioxidant-related transcription factor NRF2 in a range of malignancies at the genomic, protein expression, and clinical levels, as well as tumour immunologic analysis." (PMID 35801728, 2022). "Of note, BRCA1 proficiency appeared to be disadvantageous to tumors in the absence of platinum exposure, as tumor relapses usually re-acquired BRCA1 LOH during therapy holidays, an effect we could not evaluate in this cohort." (PMID 36344544, 2022). "The addition of a STING agonist together with a PARPi in pre-clinical models of breast cancer lacking BRCA1 increased anti-tumour immunity resulting in increased therapeutic efficacy that may also be an approach to overcoming resistance to PARP inhibition." (PMID 36230543, 2022). "However, in the recent cohort an atypical tumour phenotype was present in 15.8% (12/76) of non-BRCA1/BRCA2 MINAS cases (though not all studies presented individual patient-level data)." (PMID 34983940, 2022). "However, the associations between these genes and an HRD phenotype may be less consistent than those for BRCA1 and BRCA2 and may vary by the tumor’s tissue of origin." (PMID 35740616, 2022). "BRCA1 mutation carriers more often had a larger tumor than BRCA2 mutation carriers (pT1c 71.6% vs 63.3%, p = 0.030, data not shown) and more often had an ER-negative tumor (79.7% vs 26.4%, p < 0.001, data not shown)." (PMID 35507134, 2022). "This is particularly important because, apart from BRCA1/BRCA2 MINAS, other CSG MINAS combinations are rare and so clinicians faced with an individual with non-BRCA1/BRCA2 MINAS will often find it very difficult to predict what the implications are for tumour risks in that individual." (PMID 34983940, 2022). "For the tumor with a somatic BRCA2 mutation with LOH (M096), which was not identified as HRD by the BRCA1/2-like classifier and CHORD, the normal control was shown to contain significant contamination with tumor DNA, which is likely to have compromised the somatic mutation calling." (PMID 35662281, 2022). "Neither drug had an effect on the growth of Brca1+/+ tumours." (PMID 35107878, 2022). "Given that APC/Cdh1 is critical to the function of HR repair factors, we hypothesize that tumor cells lacking Cdh1 will be as sensitive to replication pressure as cells without BRCA1." (PMID 35627188, 2022). "Thus, because of these defects, it is not likely feasible to correct DNA damage in BRCA1-mutant tumor cells." (PMID 33767581, 2021).
tumor (continued). "Because BRCA1 is highly expressed in neuronal progenitor cells during early development and MYC is less efficient than MYCN in recruiting BRCA1, the Eilers team suggests that a cell-lineage-specific stress response enables MYCN-driven tumours to cope with deregulated RNAPII function." (PMID 34945759, 2021). "Importantly, at concentrations that elicited cell inhibition in BRCA1 or BRCA2 mutant cells, ART558 had minimal effects in non-tumour epithelial cells such as the human mammary epithelial cell lines, MCF10A, MCF12A and HMLE3, or in BRCA-gene wild type CAL51 triple-negative breast tumour cells." (PMID 34140467, 2021). "The pooled odds ratio analysis showed a significant relationship between higher PARP expression and larger tumour size, poor tumour differentiation, lymph node metastasis, distant metastasis, higher TNM stage and lymphovascular invasion, and positive immunoreactivity for Ki-67, BRCA1, and BRCA2." (PMID 34830749, 2021). "This is an interesting finding but may likely be due to chance since there were no stark differences observed in the tumor subtypes in our study cohort and the power for BRCA1 carriers was limited." (PMID 34575694, 2021). "Therefore, we tested LOH in c.9976A>T carrier cases where c.9976A>T occurred without any other pathogenic BRCA1 or BRCA2 variant and where a tumor sample was available." (PMID 33672545, 2021). "However, knocking down EpCAM failed to significantly alter radiation responses in Brca1-mutant tumor cells (data not shown), suggesting that, although EpCAM is a functional biomarker candidate, it not a promising target of therapeutics." (PMID 33767581, 2021). "Although somatic mutations in BRCA1/2 are not common in TGCT, the mutational signature associated with HR defects and high frequency of inactivation by methylation of BRCA1 and RAD51C have been reported in these tumours." (PMID 34281219, 2021). "We also include an analysis of the genomic and transcriptomic landscape of the DDR PARP genes and key HR genes (BRCA1, BRCA2, ATM, RAD51, MRE11, PALB2) in GI patient tumours (n = 1744) using publicly available datasets to identify patients that may benefit from PARPi therapeutic approaches." (PMID 34440228, 2021). "Comparison of clinical pathological features observed among women with and without alterations in the BRCA1 revealed the former were found to have high cyto-histological tumor grade, showed nodal involvement and expressed low levels of progesterone and estrogen receptors." (PMID 32063924, 2020). "This suggests that MDSCs may play a role in the initiation of Brca1 mutant tumor, not in tumor progression." (PMID 32195105, 2020). "This hypothesis is reinforced by the intrinsic subtypes of BRCA1, BRCA2 and BRCAx tumours." (PMID 33081408, 2020). "No pathogenic variants in BRCA1, BRCA2 or 13 additional HR-related genes, nor BRCA1 promoter hypermethylation or large genomic rearrangements in BRCA1, were detected in the remaining HRD tumor (case 48) nor in the two HRI tumors (case 38 and 39)." (PMID 33003546, 2020).